ST8SIA1 (ST8 alpha-N-acetyl-neuraminide alpha-2,8-sialyltransferase 1)
Diseases named in the same sentence as ST8SIA1 in open-access papers (continued):
Sharing a sentence is not in itself a finding about the gene and the disease.
melanoma (continued). "Moreover, as the ganglioside pathway preferentially leads to GD3 expression through increased ST8SIA1 activity in highly advanced metastatic melanomas, such as MBM, the expression levels of GM3 and GM2 were decreased compared to LNM." (PMID 32358995, 2020). "Triptolide was also found to indirectly inhibit ST8SIA1 in melanoma cells." (PMID 33260650, 2020). "Moreover, we demonstrated an upregulation of ST8SIA1 (GD3 synthase) as melanoma progresses from melanocytes to MBM cells." (PMID 32358995, 2020). "Consequently, the GD3 synthase gene (ST8SIA1) was highly expressed only in the melanoma cell lines examined, and GM2/GD2 synthase (B4GALNT1) was also expressed only in melanoma cells." (PMID 31611597, 2019). "Several reports have described the 5′-untranslated region (5′-UTR) of ST8SIA1 in melanoma, glioblastoma and neuroblastoma cell lines, showing a unique transcript with transcription start sites (TSS) located 400 to 650 bp upstream the initiation codon on the first exon." (PMID 23626833, 2013). "In SK MEL-2 melanoma cells, the promoter region lacks TATA and CAAT boxes, but contains putative binding sites for general transcription factors associated with cancers and inflammation (c-Ets-1, CREB, AP-1, NF-κB), with a crucial role of NF-κB in ST8SIA1 expression in SK-MEL-2 cells." (PMID 35267607, 2022). "We assessed correlation between ST8SIA1 expression and GD3 or GM3 levels in all the melanoma cell lines profiled." (PMID 32358995, 2020). "As rapid activation of the NF‐κB pathway has been suggested to enhance ST8SIA1 and GD3 expression in Fas‐induced Jurkat T cells, we examined the levels of p50 and p65 in icaritin‐treated melanoma LNM and MBM cell lines compared to untreated cells." (PMID 32358995, 2020). "We previously demonstrated that expression levels of GD3 synthase (ST8SIA1) and GM2/GD2 synthase (B4GALNT1) genes were markedly high in melanoma lines compared with melanocytes." (PMID 31611597, 2019). "Concerning GT genes involved in ganglioside biosynthesis, a functional NFκB binding site at -777/-762 pb upstream the ATG was shown to be essential for ST8SIA1 transcription in melanoma cells and inflammatory cytokines including TNF and IL-6 enhanced GD3S gene expression in melanocytes." (PMID 29698439, 2018). "However, 7,8-DHF did not suppress ST3GAL5 and ST8SIA1 mRNA expression in SK-MEL-2 or G-361 melanoma cells." (PMID 36991237, 2023). "Furthermore, we evaluated the association between ST8SIA1 expression and clinical/pathology demographics using the melanoma TCGA database; however, it is important to mention that we found no clinically annotated MBM in TCGA melanoma database (version 2019)." (PMID 32358995, 2020).
neuroblastoma (11 papers, 2012 to 2025). Neuroblastoma (NB) is the most common solid, extracranial childhood tumor. "Moreover, in high-risk and relapsed neuroblastoma, ST8SIA1 suppression by Yes-associated protein (YAP) has been implicated in resistance to GD2-targeted antibody therapies." (PMID 39860532, 2025). "This is consistent with our observation of reduced ST8SIA1 expression in MYCN-A neuroblastoma, which exhibited lower immune cell infiltration." (PMID 39860532, 2025). "Use of HDAC inhibitors enhanced GD2 expression on neuroblastoma cells through upregulation of ST8SIA1." (PMID 37670947, 2023). "We next addressed if the trans-interaction between SLAMF7 on macrophages and neuroblastoma cells could occur by examining SLAMF7 expression on the tumor cells relative to those of B4GALNT1 (GD2 synthase gene) and ST8SIA1 (GD3 synthase gene) in high-risk neuroblastoma tissues." (PMID 35525858, 2022). "Use of EZH2 inhibitors in various potentially GD2-positive cancers such as neuroblastoma and Ewing sarcoma led to increased GD2 expression through upregulation of ST8SIA1, and in some cases B4GALNT1." (PMID 37670947, 2023). "B4GALNT1 and ST8SIA1 are responsible for the expression of GD2, the well-recognized target of neuroblastoma immunotherapy." (PMID 35525858, 2022).
triple-negative breast carcinoma (10 papers, 2015 to 2024). An invasive breast carcinoma which is negative for expression of estrogen receptor (ER), progesterone receptor (PR), and human epidermal growth factor receptor 2 (HER2). "The elevated GD3S expression in triple negative breast cancer (TNBC) cells and tissues was associated with hypomethylation of the ST8SIA1 gene." (PMID 34208013, 2021). "The up-regulated expression of GD2 antigen in cancer cells was reported to be related with NF-κB and its biosynthesis was regulated by GD3 synthase (ST8SIA1), especially in the model of triple-negative breast cancer." (PMID 36617554, 2023). "For example, inhibiting ST8SIA1 can sensitize triple-negative breast cancer to chemotherapy via suppressing FAK/AKT/mTOR." (PMID 36034784, 2022). "A further study shed light on the role of ST8SIA1 in triple negative breast cancers (TNBC), showing that ST8SIA1 is highly expressed in primary TNBC, and its knockdown inhibits orthotopic xenograft growth of TNBC cells and abolishes lung metastases." (PMID 33921986, 2021). "And ST8SIA1 knockout completely blocks the growth and metastasis of triple negative breast cancer cells in vitro and in vivo." (PMID 34738863, 2021). "Using Kaplan–Meier methods, we determined that high expression of ST8SIA1 was associated with poor 10-year OS in all patients, triple-negative breast cancer (TNBC), and non-TNBC patients, and poor disease-free survival (DFS) rates particularly in TNBC." (PMID 33260650, 2020).
glioblastoma (8 papers, 2013 to 2024). The most malignant astrocytic tumor (WHO grade IV). "Notably, ST8SIA1 expression is increased in the neurospheres and human glioblastoma multiforme tissues, whereas the inhibition of ST8SIA1 results in decreased glioblastoma stem cell-associated properties." (PMID 35267607, 2022). "The promoter region of the ST8SIA1 gene has been described in melanoma, glioblastoma, and breast cancer cell lines, showing a unique transcript with transcription start sites located 450 to 690 bp upstream of the initiation codon on the first exon." (PMID 34200284, 2021). "The implication of ST8Sia1 in stemness with c-Met signaling downstream of this enzyme was also found in experimental models of glioblastoma." (PMID 34975914, 2021). "In glioblastoma cells, analysis of the ST8SIA1 promoter has shown the role of AREB6 and Elk-1 transcription factors in GD3 synthase gene transcription." (PMID 34200284, 2021). "In addition, ST8SIA1 is one of the key drivers for malignancy in glioblastoma." (PMID 34943806, 2021).
glioma (8 papers, 2014 to 2024). A benign or malignant brain and spinal cord tumor that arises from glial cells (astrocytes, oligodendrocytes, ependymal cells). "Lack of ST8SIA1 expression resulted in the prolonged lifespan of glioma-bearing mice, and low-grade pathology in generated gliomas, by modulating the AP2/MMP9 axis." (PMID 35267607, 2022).
breast tumors (5 papers, 2013 to 2025). "Clinical studies have also shown that high expression of ST8SIA1, the gene coding the GD3 synthase (GD3S), is associated with Estrogen Receptor (ER) negativity and high histological grade of breast tumors." (PMID 23626833, 2013). "Here, we describe the main transcript of the GD3S coding gene ST8SIA1 expressed in breast tumors." (PMID 23626833, 2013). "A higher expression of ST8SIA1 and MET was also observed in the basal-like subtype of human breast tumors." (PMID 35267607, 2022).
prostate carcinoma (5 papers, 2022 to 2024). A carcinoma that arises from epithelial cells of the prostate gland. "In prostate cancer cells, ST8SIA1 is a target of lncRNA MIR4435-2HG." (PMID 35267607, 2022). "The knockdown of lncRNA MIR4435-2HG expression inhibited prostate cancer cell malignant properties in vitro and in vivo, whereas the inhibition of ST8SIA1 expression decreased the effects of miR4435-2HG, both in vitro and in vivo, by blocking the activation of the FAK/AKT/β-catenin pathway." (PMID 35267607, 2022). "In prostate cancer tissues and cell lines, MIR4435-2HG promotes ST8SIA1 and up-regulates p-AKT levels." (PMID 35784328, 2022).
bladder cancer (4 papers, 2022 to 2025). "Conversely, increased expression levels of ST8SIA1 (the gene that codes for the glycosyltransferase that converts GM3 into GD3), was associated with reduced proliferation, migration, and invasion of bladder cancer cells." (PMID 40252176, 2025). "Conversely, the mRNA expression levels of ST8SIA1 (the enzyme that converts GM3 to GD3) are significantly decreased in bladder cancer tumors compared to normal bladder tissues, and its low expression is associated with increased pathological grade and invasiveness." (PMID 40252176, 2025). "Ultimately, strategies involving ST3GAL5 and ST8SIA1 overexpression, or inhibition of ST3GAL6, FUT4 and FUT7, could offer new therapeutic avenues for bladder cancer." (PMID 40252176, 2025). "Because GM3 has been reported to suppress EGFR phosphorylation in bladder cancer cell lines, it was suggested that further sialylation of GM3 by ST8SIA1 may enhance this inhibitory effect by reducing EGFR, JAK, and STAT3 phosphorylation levels." (PMID 40252176, 2025). "Regarding other potential sialyltransferase targets, on one hand, ST8SIA1 may suppress the JAK-STAT signaling pathway, thereby attenuating the proliferation and metastasis of bladder cancer." (PMID 40252176, 2025).
colorectal cancer (4 papers, 2020 to 2022). A primary or metastatic malignant neoplasm that affects the colon or rectum. "Another study suggested that microRNA-33a and let-7E inhibited the progression of colorectal cancer by targeting ST8SIA1." (PMID 34738863, 2021).
liver cancer (3 papers, 2021 to 2024). An epithelial or non-epithelial malignant neoplasm that arises from the liver. "Three genes, namely, CLEC4G, LCP2, ST8SIA1 are acting as biomarkers in liver carcinoma." (PMID 38674383, 2024). "Besides, ST8SIA1 was found down-regulated in pancreatic and liver cancer, and could inhibit these two types of tumor progression." (PMID 34738863, 2021).
lung carcinoma (3 papers, 2022 to 2024). "Next, PTGES, ST8SIA1 and PTGS2 expression levels were evaluated in patients with lung cancer (GSE31210) and IPF using microarray datasets." (PMID 39417702, 2024).
brain tumors (2 papers, 2024 to 2025). "We found that genes responsible for GD2 synthesis (B4GALNT1 and ST8SIA1) and CD276, encoding B7-H3, were expressed at similar or lower levels in MB than in other brain tumors." (PMID 41159102, 2025).
Clear-Cell Renal Cell Carcinoma (2 papers, 2022 to 2025). "Interestingly, high ST8SIA1 expression has been correlated with the increased infiltration of CD4+ and CD8+ T cells, neutrophils, dendritic cells, and M1 macrophages in clear-cell renal cell carcinoma." (PMID 39860532, 2025).
gastric cancer (2 papers, 2021 to 2025). A primary or metastatic malignant neoplasm involving the stomach. "In gastric cancer, NR2F1-AS1 enhances cell growth through various axes, including miR-29a/VAMP7, miR-190a/PHLDB2/AKT3, SPI1/ST8SIA1, and miR-493-5p/MAP3K2." (PMID 40828427, 2025). "In gastric cancer, NR2F1-AS1 acts as an EMT-inducing lncRNA that enhances cell motility via the miR-29a/VAMP7 axis, activation of AKT3 through miR-190a/PHLDB2, SPI1-mediated transcriptional upregulation of ST8SIA1, and miR-493-5p/MAP3K2 signaling." (PMID 40828427, 2025).
lymph node metastasis (2 papers, 2020 to 2022). "Our results demonstrated that ST8SIA1 upregulation favors metastatic melanoma progression in lymph node metastasis (LNM) and MBM development; moreover, we demonstrated that high ST8SIA1 expression is a significant independent prognostic factor for LNM patients in multivariable analysis." (PMID 32358995, 2020).
meningioma (2 papers, 2020 to 2021). A generally slow growing tumor attached to the dura mater. "In the malignant meningioma cell line, we observed changes in expression of sialyltransferases (ST3GAL1/2/3, ST6GALNAC5, and ST8SIA1) after glycation, which correlates with less aggressive behavior." (PMID 34943806, 2021).
benign meningioma (1 paper, 2021). A grade I, slowly growing meningioma. "In the benign meningioma cell line, glycation led to differences in expression of sialyltransferases (ST3GAL1/2/3/5/6, ST6GAL1/2, ST6GALNAC2/6, and ST8SIA1/2), which are known to play a role in tumor progression." (PMID 34943806, 2021).
brain cancer (1 paper, 2024). A primary or metastatic malignant neoplasm affecting the brain. "Moreover, we also identified other clinically relevant GRGs, as is the case of ST8SIA1 and B4GALNT1, which contribute to the synthesis of ganglioside GD2, in brain cancers." (PMID 38384845, 2024).
Ewing sarcoma (1 paper, 2022). A small round cell tumor that lacks morphologic, immunohistochemical, and electron microscopic evidence of neuroectodermal differentiation. "EZH2 directly binds to promotor regions of ST8SIA1, and inhibition of EZH2 enhances the expression of this gene in Ewing sarcoma cells." (PMID 36313564, 2022).
insulinomas (1 paper, 2017). "To determine whether insulinomas are also heterogeneous with respect to the hallmark markers of human beta cell heterogeneity, we explored CD9 and ST8SIA1 expression in our beta cell and insulinoma transcriptome data sets." (PMID 28974674, 2017). "Indeed, both ST8SIA1 and CD9 expression were highly variable among both human beta cells as well as insulinomas." (PMID 28974674, 2017).
medulloblastoma (1 paper, 2025). A malignant, invasive embryonal neoplasm arising from the cerebellum. "For instance, medulloblastoma group 3 is characterized by predominant GM3 expression, which in the presence of ST8SIA1 and B4GALNT1 can be converted to GD2." (PMID 41424948, 2025).
ophthalmoplegia (1 paper, 2024). Weakness or paralysis of at least one of the muscles controlling the movement of the eye. "St8sia1 has been identified as a potential candidate in the acquisition of experience-dependent plasticity in murine visual cortex, and polymorphisms in the human ST8SIA1 have been identified in patients with treatment-resistant ophthalmoplegia." (PMID 39649107, 2024).
ovarian carcinoma (1 paper, 2024). A malignant neoplasm originating from the surface ovarian epithelium. "CRISPR-Cas9-knocking-mediated truncation of endogenous E-cadherin in ovarian cancer cells induces EMT, which results in a decrease in globoside GSLs, while the deletion of ST8SIA1, which synthesizes GD3, induces mesenchymal–epithelial transition." (PMID 39329960, 2024).
periodontitis (1 paper, 2023). An acute or chronic inflammatory process that affects the tissues that surround and support the teeth. "At the genetic level, it has been reported that the elevated expression of ST8SIA1, a periodontitis risk gene, caused by weakening of Bach1's binding to effect T allele of its coinherited variants is a genetic cause of periodontitis." (PMID 37602966, 2023).
type 1 diabetes (1 paper, 2024). "Correlation analysis has revealed ST8SIA1 as one of the genes with integrative changes in RNA expression and DNA methylation in the offspring born to women with pregestational type 1 diabetes (T1DM)." (PMID 39649107, 2024).
tumor (35 papers, 2013 to 2025). "ST8SIA1 expression levels were negatively correlated with tumor purity and positively associated with infiltrated immune cells and expression of immune checkpoint genes." (PMID 35873547, 2022). "Inhibition of GD3 or its synthesizing enzyme, GD3 synthase (ST8SIA1), impairs these tumor-promoting processes, reduces tumor growth, and enhances sensitivity to temozolomide, highlighting GD3 as a compelling therapeutic target." (PMID 40868137, 2025). "Lastly, in the ST8SIA family, ST8SIA1 and 4 had higher expressions in tumor tissues compared to normal tissues." (PMID 38067186, 2023). "Most importantly, ST8SIA1 knockdown annihilated tumorigenicity in an immunodeficient mice model, preventing tumor formation." (PMID 35267607, 2022). "Several glycosyltransferases, including MGAT5, FUT8, ST6GAL1, ST6GALNAC1 and ST8SIA1 have an established reputation as tumor-promoting enzymes." (PMID 35565254, 2022). "To verify the expression level of ST8SIA1, we performed the immunohistochemical analysis of 46 ccRCC tumor tissues and 37 adjacent normal kidney tissues." (PMID 35873547, 2022). "In the Oncomine database, meta-analysis also revealed ST8SIA1 was highly expressed in the tumor tissue (p = 0.03)." (PMID 35873547, 2022). "The ST8SIA1 expression level was positively correlated to the abundance of most tumor-infiltrating lymphocytes and immunoinhibitory and immunostimulatory gene expressions across different cancers from TCGA." (PMID 35873547, 2022). "In CRC, miR-33a inhibits tumour angiogenesis and metastasis by regulating ST8SIA1, and the overexpression of miR-33a can inhibit CRC cell resistance." (PMID 33865381, 2021). "Then, in UALCAN database, we found JUP and ITGB4 were higher expressed in tumor while ST3GAL5 and ST8SIA1 were lower expressed in tumor." (PMID 34402716, 2021). "5′-UTR amplification was performed for Hs578T cells and 3 tumor samples representative of the different levels of ST8SIA1 expression (#137, #142 and #144) by 5′-RACE as described in the Material and Methods section." (PMID 23626833, 2013). "The total expression of ST8SIA1 was higher in tumor samples compared to Hs578T cells and T1 accounted for 50 to 100% of the total transcripts, making it the main ST8SIA1 transcript across this series of tumor samples." (PMID 23626833, 2013). "ST8SIA1 expression was also positively correlated with the grade of tumor (Rho = 0.198, p < 0.001)." (PMID 35873547, 2022). "Elevated ST8SIA1 was observed in the tumor tissues compared with adjacent normal tissues and associated with higher T stage and advanced TNM stage (all p < 0.05)." (PMID 35873547, 2022). "The authors of several studies reported that ST8SIA1 could promote tumor growth, metastasis, and chemoresistance through the FAK/Akt/mTOR and Wnt/β-catenin signaling pathways in TNBC cell lines." (PMID 33260650, 2020). "Both ST8SIA1 and ST6GALNAC2 belong to the sialyltransferase (ST) family of enzymes, which promote tumour growth and metastasis." (PMID 33865381, 2021). "EZR-negative tumor cells also show the significant upregulation of CD109, ID4, ST8SIA1, and NR4A1 genes." (PMID 32679794, 2020). "In ERα positive tumours, E2 blocks its expression by preventing NFκB from binding to the GD3S gene ST8SIA1 (ST8 alpha-N-acetyl-neuraminide alpha-2,8-sialyltransferase 1) core promoter." (PMID 27160081, 2016). "Conversely, TQ treatment resulted in the downregulation of several genes overexpressed in GBM cells, including potential oncogenes like AEBP1, MIAT, GHR, LMO1, ELF3, and genes involved in tumor proliferation and migration such as EPHA4, COL3A1, PCDH10, ROBO1, ADAMTS5, PCDH18, ST8SIA1." (PMID 39874307, 2025). "Based on the TIMER and CIBERSORT algorithms, a negative relationship between ST8SIA1 expression and tumor purity was observed (Rho = -0.334; p < 0.001)." (PMID 35873547, 2022).